CYTL1 (cytokine like 1)
Diseases named in the same sentence as CYTL1 in open-access papers (continued):
Sharing a sentence is not in itself a finding about the gene and the disease.
osteoarthritis (3 papers, 2019 to 2023). A noninflammatory degenerative joint disease occurring chiefly in older persons, characterized by degeneration of the articular cartilage, hypertrophy of bone at the margins and changes in the synovial membrane. "Collectively, multiple lines of evidence suggest that, rather than regulating physiological cartilage and bone development, Cytl1 is involved mainly in the maintenance of cartilage homeostasis, and that loss of Cytl1 function is associated with osteoarthritis progression." (PMID 31089746, 2019). "Cytl1 appears to play a role in chondrogenesis, cartilage homeostasis, and osteoarthritis progression." (PMID 31089746, 2019). "In addition to its role in cartilage homeostasis and osteoarthritis progression, Cytl1 has been found to be involved in the regulation of macrophage migration." (PMID 31089746, 2019). "Several other non-structural components with important cartilage ECM roles in development or osteoarthritis were also downregulated, including proteoglycan-related gene 4/lubricin (Prg4), procollagen C-endopeptidase enhancer 2 (Pcolce2), and Cytokine-like 1 (Cytl1)." (PMID 30793021, 2019). "In this review, we explore evidence suggesting that Cytl1 may be involved in the regulation of chondrogenesis, cartilage homeostasis and osteoarthritis progression, accompanied by the modulation of Sox9 and insulin-like growth factor 1 expression." (PMID 31089746, 2019). "Collective evidence suggests that Cytl1 may induce chondrogenesis, and is required for cartilage homeostasis, and the prevention of osteoarthritis progression, rather than the regulation of cartilage and bone development." (PMID 31089746, 2019). "More recently, Cytl1, was identified as being differentially expressed in post-traumatic osteoarthritis (PTOA), indicative that Cytl1 may be a potential target for specific intervention in early PTOA, and further suggesting the role of Cytl1 in osteoarthritis development." (PMID 31089746, 2019).
heart failure (2 papers, 2016 to 2019). Inability of the heart to pump blood at an adequate rate to meet tissue metabolic requirements. "Thus further studies are required to demonstrate the detailed mechanisms by which Cytl1 may mediate pro-angiogenic functions and may be implicated in the pathogenesis of cardiac fibrosis and heart failure." (PMID 31089746, 2019). "As MCP-1 plays an important role in cardiac fibrosis and heart failure (HF), we investigated the role of Cytl1 in a mouse model of CF and HF." (PMID 27835665, 2016). "Interestingly, Cytl1, also appears to be involved in the pathogenesis of cardiac fibrosis and heart failure (HF), and may be structurally and functionally related to MCP-1 (or CCL2)." (PMID 31089746, 2019). "In addition, Cytl1 also appears to activate the TGF-beta-SMAD signalling pathway via an unidentified receptor, and play an important role in cardiac fibrosis and heart failure." (PMID 31089746, 2019).
lung carcinoma (2 papers, 2023). "By reducing STAT3 phosphorylation, CYTL1 prevents lung cancer tumor spread." (PMID 37745303, 2023).
lung squamous cell carcinoma (2 papers, 2017 to 2019). "Using a combination of the whole-genome DNA methylation pattern and the gene-expression profile, Cytl1 was also identified as one of the candidate genes that is regulated by DNA methylation in human lung squamous cell carcinoma." (PMID 31089746, 2019). "A recent genome-wide analysis of DNA methylation and gene expression changes in lung squamous cell carcinoma identified several methylation-driven genes, including CCDC37, CYTL1, CDO1, SLIT2, LMO3 and SERPINB538." (PMID 28198450, 2017).
alcohol dependence (1 paper, 2019). Physical and psychological dependence on alcohol. "A recent genome-wide association study (GWAS) found that certain haplotypes within the Cytl1 gene were significantly associated with an increased risk of alcohol dependence (AD), suggesting that the Cytl1 gene may play an important role in the susceptibility to AD." (PMID 31089746, 2019).
benign prostatic hypertrophy (1 paper, 2019). "Further, previous studies have revealed that Cytl1 expression together with secreted CXC-type chemokinesis was associated with benign prostatic hypertrophy." (PMID 31089746, 2019).
chronic granulocytic leukemia (1 paper, 2023). "Secretory CYTL1 enhances MAPK/ERK pathway activation through C-C chemokine receptor type 2 in chronic granulocytic leukemia (CMML) (CCR2)." (PMID 37745303, 2023).
immunotoxicity (1 paper, 2021). "The authors elaborate that the gene expression related to increased PFAS levels was indicative of immunotoxicity because of association with immunomodulatory genes (e.g., CYTL1, IL27)." (PMID 34712855, 2021).
myocardial infarction (1 paper, 2016). Gross necrosis of the myocardium, as a result of interruption of the blood supply to the area, as in coronary thrombosis. "We found that Cytl1 expression was highly elevated in mice with severe CF associated with pressure overload, myocardial infarction (MI), and ischemia-reperfusion (I-R) injury." (PMID 27835665, 2016).
squamous cell carcinoma (1 paper, 2023). A carcinoma arising from squamous epithelial cells. "The previous literature had reported that CYTL1 was a small widely expressed secreted protein, which closely related to CCL2, and the expression was also downregulated in the squamous cell carcinoma of the lung." (PMID 36838330, 2023).
tumor (15 papers, 2012 to 2024). "In other cancers, however, CYTL1 exhibits the opposite effect, acting as a tumour suppressor and inhibiting tumourigenesis." (PMID 37702613, 2023). "DNA methylation analysis also revealed the methylation of multiple genes (FRMD6-AS2, SESN3, CYTL1, MIR4429, HIF3A, and ATP1B2) associated with tumor growth suppression." (PMID 36975488, 2023). "The results showed that CYTL1 was not significantly correlated with the stromal component in the tumor microenvironment, while high CYTL1 expression significantly inhibited immune infiltration in the tumor microenvironment." (PMID 37745303, 2023). "We found that CYTL1 was underexpressed in tumor tissues (n = 375) relative to that in normal tissues (n = 32) (p ≤ 0.001); to exclude experimental bias, we chose paired sample (n = 27) analysis." (PMID 36825034, 2023). "Taken together, our study reveals the function of CYTL1 as an intrinsic tumor suppressor to maintain metabolic homeostasis in tumors, which is helpful by providing potential points of therapeutic intervention against cancers." (PMID 35115484, 2022). "The trend of profound reduction in CYTL1 level in advanced tumors suggests the possibility that CYTL1 can be recognized as a suppressor that hinders tumor progression." (PMID 35115484, 2022). "Most of these genes were reported to be associated with tumor metastasis, such as TDO2, CYTL1, and LDB2." (PMID 35982908, 2022). "It is hypothesized that the primary factor influencing CYTL1 transcript levels is the kind of tumor." (PMID 37745303, 2023). "Additionally, the methylation of FRMD6-AS2, SESN3, CYTL1, MIR4429, HIF3A, and ATP1B2, which are associated with tumor growth suppression, was detected by DNA methylation analysis." (PMID 36975488, 2023). "In our research, low CYTL1 expression (tumor vs. normal) was noted in patients with STAD." (PMID 36825034, 2023). "In contrast, in ACC, CYTL1 acted as a tumor suppressor and prolonged the survival of patients." (PMID 37745303, 2023). "In addition, the methylation of FRMD6-AS2, SESN3, CYTL1, MIR4429, HIF3A, and ATP1B2, which are associated with tumor growth suppression, was also detected." (PMID 36975488, 2023). "Similarly, the expression level of CYTL1 in tumor tissues was lower than that in normal tissues (t = −4.918, p ≤ 0.001)." (PMID 36825034, 2023). "In the present study, we reveal that CYTL1 may be a novel tumor suppressor that is capable of blocking the metabolic switching from OXPHOS to glycolysis." (PMID 35115484, 2022). "Our results reveal, for the first time, that CYTL1 is a novel tumor suppressor." (PMID 35115484, 2022). "As a result of decreasing STAT3 phosphorylation, CYTL1 could inhibit tumor metastasis." (PMID 39867879, 2024). "Moreover, CYTL1 might serve as a tumor suppressor with broad inhibitory effects on tumor metastasis and the phosphorylation of STAT3 in multiple tumor models." (PMID 36276067, 2022). "Taken together, intracellular CYTL1 may be a novel tumor suppressor." (PMID 35115484, 2022). "CYTL1 has been reported to inhibit STAT3 phosphorylation, and a decrease in STAT3 phosphorylation expression was accompanied by an increase in anti-angiogenic effects, thereby inhibiting tumor progression." (PMID 36899891, 2023). "CYTL1 is highly expressed in HP, though almost not expressed in all three tumor types." (PMID 22693581, 2012).
cancer (7 papers, 2019 to 2024). A tumor composed of atypical neoplastic, often pleomorphic cells that invade other tissues. "CYTL1 is a secreted protein involved as a cytokine in the regulation of some cancers and cellular inflammation." (PMID 37702613, 2023). "Cytokine-like 1 (CYTL1, also known as C17 or C4ORF4) is a secreted protein that has shown a deregulated expression profile across cancers and has also been implicated in carcinogenesis." (PMID 36389725, 2022). "Previous studies have revealed that CYTL1 plays opposite roles in distinct cancer types." (PMID 35898512, 2022).
infection (2 papers, 2019 to 2023). The state of being infected such as from the introduction of a foreign agent such as serum, vaccine, antigenic substance or organism. "These are involved in smooth-muscle function (FGFR1, GATA5 and STIM1), tissue organization (ADAMTS10), alveolar and epithelial function (ABCA3 and CLDN18), and inflammation and immune response to infection (CFH, CYTL1, HMCN1, LRBA and STIM1)." (PMID 36914875, 2023).
heart diseases (1 paper, 2016). "Therefore, Cytl1 might provide a novel strategy for the treatment of heart diseases such as CF and HF." (PMID 27835665, 2016).
CYTL1 also shares sentences with these, for which no sentence is quoted: cervical cancer (1 paper); chronic kidney disease (1); cutaneous melanoma (1); endometrial cancer (1); familial colorectal cancer (1); immune system disease (1); nephrotic syndrome (1); nevus (1); Stomach Adenocarcinoma (1); stomach cancers (1); tuberculosis (1).